ENSG00000200991
Synonyms: LOC124900361
Gene: Small nucleolar RNA gene on chromosome 15 (84,852,498 to 84,852,615, reverse strand). Ensembl gene ENSG00000200991.
Gene Ontology:
Biological process: RNA processing
Cellular component: nucleolus
Homologues: Paralogues in human: SNORA25 (89% identical), SNORA25B (84% identical).